CDH1 (cadherin 1)
Diseases named in the same sentence as CDH1 in open-access papers (continued):
Sharing a sentence is not in itself a finding about the gene and the disease.
breast carcinoma (continued). "Interestingly enough, using the cBioportal, we found that the 9 ERBB2 mutated ILC cases of TCGA 2015 were CDH1 mutated with a significant correlation with a Fisher's exact test (p = 0.02) calculated among breast carcinomas of other histological subtypes." (PMID 27602491, 2016). "Our meta-analysis demonstrated that the -160C/A polymorphism in the CDH1 gene might contribute to breast cancer susceptibility." (PMID 27349965, 2016). "Our study suggests that CDH1-altered ILC patients with ERBB2 mutations may represent an actionable group of patients who could benefit from targeted breast cancer therapy." (PMID 27811364, 2016). "For survival analyses, the results demonstrated that the minor allele homozygotes of rs13689 and haplotype TGC in CDH1 were linked with unfavorable event-free survival of breast cancer, whereas, rs4783689 of CDH1 showed the opposite effect under dominant model." (PMID 26285011, 2015). "For association analyses of germline variants with breast cancer susceptibility, the results showed that rs7200690, rs7198799, rs17715799, rs13689 and diplotype CGC/TGC (rs7200690 + rs12185157 + rs7198799) in CDH1 as well as rs2293303 in CTNNB1 were associated with increased breast cancer risk." (PMID 26285011, 2015). "H233Q in CDH1 was found to be associated with breast cancer." (PMID 26518340, 2015). "However, the identification of large numbers of early stage gastric and breast cancers in CDH1 germline mutation carriers demonstrates that E-cadherin loss can also influence the initiation of cancer." (PMID 25079037, 2014). "CDH1 is inactivated by mutation or promoter hypermethylation in e.g. gastric and breast cancers." (PMID 24165089, 2013). "HDGC family history has been associated with breast cancer, the etiology of which may involve germline mutations in the cadherin-1 (CDH1) gene." (PMID 23953708, 2013). "Other “cancer drivers” in luminal BC from young patients were CDH1, NF1 and PTEN, which are classical TSG associated with breast cancer predisposition, as well as AKT, a classical BC oncogene." (PMID 39208653, 2024). "The implication of germline pathogenic variants in the CDH1 gene has been discussed for BC, particularly lobular breast cancer (LBC)." (PMID 36553480, 2022). "Therefore, the cleavage of E-cadherin by gamma-secretase subunits encoded in Chr1q and the decreased transcription of the CDH1 gene produced by 16q-loss can represent cooperating mechanisms underlying the decreased function of adherens junctions in breast cancer." (PMID 33808143, 2021). "CDH1 mutation is closely related to lobular breast cancer, and the lifetime risk of developing BC in those with a CDH1 mutation is approximately 39%." (PMID 34926254, 2021). "Thus, noise in the partitioning of parent cell biomolecules among the daughter cells can further alter the subpopulation structure, and may underlie different bimodal distributions of surface CDH1 expression seen in breast cancer cell lines." (PMID 32676163, 2020). "Therefore, ROS1 inhibitors may be of benefit for patients with CDH1 mutated breast cancers, in combination with PI3K or AKT inhibitors, with or without immunotherapy, and warrant further investigation in early clinical trials." (PMID 32983983, 2020). "Besides CDH1, our results demonstrated that GC pathogenic variants are distributed across a number of susceptibility genes and reinforced the emerging link between gastric and breast cancer predisposition." (PMID 31514334, 2019).
breast carcinoma (continued). "Moreover, somatic CDH1 mutations were reported in breast cancer, lobular carcinoma in situ (LCIS)." (PMID 30975222, 2019). "Furthermore, high expression of EMT-induced markers (vimentin, α-smooth muscle actin (a-SMA), N-cadherin, cadherin 11, SpArC, laminin and fascin) with simultaneous low expression of E-cadherin has been associated with poor prognosis in patients with breast cancer." (PMID 30526687, 2018). "Thus, it is possible that our observed prevalence of primary breast carcinomas with a CDH1 mutation, which was higher than the prevalences at most other sites, could be inflated relative to what one would find in a population-based sample." (PMID 29156750, 2017). "In addition, the presence of A allele of CDH1 -160 C/A polymorphism may play an important role in metastasis of breast cancer." (PMID 29285016, 2017). "We have also shown in the PMC42 human breast cancer model system that cellular proliferation was associated with an epithelial phenotype because the stable knockdown of ZEB1 in PMC42-ET cells resulted in CDH1 reexpression along with an increased proliferative rate." (PMID 28750639, 2017). "In addition, we determined a molecular mechanism by which DNMT3B7 promotes tumor progression in breast cancer cells through hypermethylation and loss of CDH1/E-cadherin expression, altered β-catenin localization, and subsequent changes in cell adhesion, proliferation, and growth in soft agar." (PMID 25607950, 2015). "In addition, it was recently shown that PUF60 is part of a long non-coding RNA (lncRNA)-associated ribonucleoprotein (RNP) complex, which regulates breast cancer metastasis through modulation of a translational regulatory lncRNA (treRNA), which suppresses the translation of E-cadherin (CDH1) mRNA." (PMID 26497854, 2015). "MAGT1 mutations were not statistically significantly associated with overall survival (OS) in breast cancer, but MAGT1 mutations were closely associated with ERBB2 and CDH1." (PMID 42006149, 2026). "Breast cancer cells treated with recombinant COMP or engineered to overexpress COMP exhibited a marked decrease in the epithelial marker CDH1 and an increase in mesenchymal markers such as VIM and VCAN." (PMID 41689303, 2026). "An anti-mouse CDH1 mAb reduced lung metastasis from genetically modified MMTV-PyMT mammary tumors or orthotopically grafted 4T1 tumors." (PMID 41459333, 2026). "Screening young women for CDH1 mutations, especially those with a family history of LBC or early-onset breast cancer, is a key preventive strategy." (PMID 40366456, 2025). "Genes central to the main female-biased cancers (melanoma, gastric and thyroid), breast cancer and ESR1, which encodes oestrogen receptor-α (ERα), include CDH1 (which encodes E-cadherin), CCND1 (cyclin D1), BRAF and KRAS." (PMID 40500450, 2025). "Olsalazine, utilized in the treatment of ulcerative colitis, elevates CDH1 gene expression, which encodes E-cadherin, thus inhibiting EMT in MDA MB-231 breast cancer cells." (PMID 40006021, 2025). "LSD1‐mediated demethylation of H3K4me2 on the E‐cadherin (CDH1) promoter can also active EMT in breast cancer." (PMID 41415713, 2025). "miR-9 has been found to be upregulated in breast cancer cells and promote cell motility and invasiveness by directly targeting E-cadherin, cadherin 1 (CDH1)." (PMID 40486878, 2025). "In aggressive breast cancer cells, abnormally elevated methylation levels at CDH1 are observed, which is associated with increased E-cadherin expression." (PMID 40006021, 2025).
breast carcinoma (continued). "Germline mutations in the CDH1 gene are strongly associated with hereditary diffuse gastric cancer (HDGC) and lobular breast cancer (LBC), a rare and invasive subtype of breast cancer." (PMID 40757085, 2025). "In contrast, KHK-A acts as a nuclear protein kinase upon fructose stimulation and represses CDH1, thereby facilitating breast cancer metastasis." (PMID 38200154, 2024). "Somatic mutations in CDH1 are found in around 50% of lobular breast cancers, while GATA3 mutations occur in approximately 10% of breast cancers." (PMID 39329702, 2024). "Mutations of CDH1 are the most frequently detected mutations in ILC and are characteristic of this subtype of breast cancer." (PMID 39594781, 2024). "Reactivated CDH1 suppressed the Wnt/β-catenin pathway, which confers breast cancer stem cell properties in breast cancer cells." (PMID 38542669, 2024). "Our findings revealed a positive correlation between CDH1 methylation and the presence of TILs (r = 0.5; p-value < 0.05), shedding light on an aspect of breast cancer biology warranting further investigation." (PMID 38713384, 2024). "In the present study while whole blood exposure to hormone-therapy treated breast cancer cells decreased ESR1 expression substantively, corresponding changes in EMT-associated genes indicated higher levels of CDH1 and vimentin in T47D cells than MCF7 cells." (PMID 38233507, 2024). "In particular, the expression of TWIST1 in MCF7 breast cancer cells induced Vim and Snai2 expression but repressed CDH1 and ESR1 expression." (PMID 38893094, 2024). "It has been discovered that increased levels of one of the epithelial sodium channel (ENaC) subunits, the α-ENaC, correlate with the increased expression of E-cadherin (CDH1), a protein whose mutations play an important role in breast cancer development." (PMID 38732186, 2024). "Their data showed that RUNX1, PTEN, MAP3K1, and CDH1 had the highest impact in distinguishing survival curves of premenopausal and postmenopausal breast cancer." (PMID 38919805, 2024). "And when we investigate if specific mutations were enriched in small or large tumors, we found only two genes, HRAS in small bladder cancer tumors and CDH1 in large breast cancer tumors." (PMID 39068253, 2024). "The proband was a DH PSV carrier in the CDH1 and PMS2 genes, which cause Hereditary Diffuse Gastric Cancer (and breast cancer) and Lynch syndrome, respectively." (PMID 39102164, 2024). "Instead, in breast cancer cells, PEITC can target breast cancer stem cells through the epigenetic reactivation of cadherin 1, a tumor suppressor gene, by inhibiting DNMT and HDAC activity, thus demethylating its promoter site." (PMID 39858410, 2024). "CDH1 is a transmembrane glycoprotein that is primarily responsible for cell adhesion, and its downregulation in tumors led to increased invasiveness in breast cancer and lung cancer." (PMID 38114659, 2023).
breast carcinoma (continued). "In the current Swedish national breast cancer guidelines the syndrome genes with a very low frequency of findings (CDH1, PTEN, STK11) have been excluded from the routine clinical gene panel." (PMID 37563628, 2023). "CDH1 mutated patients exhibited higher immune scores than wild-type patients in breast cancer, which supports our results that the TME of breast cancers correlates with CDH1 mutations." (PMID 36869083, 2023). "We found that VISTA expression correlated negatively with CDH1 (r= -0,3114, p <0.001) and positively with all the mesenchymal markers in breast cancer patients." (PMID 37152039, 2023). "ZEB1-KO resulted in rather unexpected results, since both miRNA-200c-3p levels and CDH1 expression levels remained unchanged in the HS578T-Hyg ZEB1-KO breast cancer cells and M13HS ZEB1-KO tumor hybrids." (PMID 38139138, 2023). "The data showed that the mRNA expression of CDH1 negatively correlated with that of ZHX2 in breast cancer." (PMID 37460540, 2023). "CRISPR/Cas9 knockdown of CTNNA1 and CDH1 reverses the inhibitory effect of Beclin-1 on breast cancer cell proliferation." (PMID 36741258, 2023). "The co-mutation of CDH1 with PIK3CA and ERBB2 contributes to endocrine resistance in breast cancer patients with invasive lobular carcinoma." (PMID 37426414, 2023). "The predicted interaction between CDH1 and RUNX1 is consistent with the observation of significant enrichment of RUNX1 binding on E-cadherin (CDH1) in breast cancer cells." (PMID 36928529, 2023). "Hypermethylation of RASSF1A, CCDN2, HIN1 and APC correlates mainly with HR+ breast cancer, whereas hypermethylation of CDH1 and CDH13 is more frequent in TNBC patients." (PMID 38169859, 2023). "Recently, gene screening data by next-generation sequencing (NGS) has demonstrated hereditary associations involving BRCA1/2, CDH1, BRIP1, and PTEN between breast cancer and ovarian cancer." (PMID 36810560, 2023). "Another epigenetic regulatory mechanism of metastasis in breast cancer is CDH1 promoter methylation." (PMID 36810560, 2023). "In the tumorigenesis models of breast cancer, it has been found that the deletion of E-cadherin (also known as CDH1) encourages angiogenesis and anoikis resistance, which in turn contributes to the development of metastatic disease." (PMID 37114037, 2023). "The expression of cdh1 was enhanced in mouse breast cancer tumors after Salinivenus iranica treatment, and it was similar to the effect of Salinomycin on mouse breast cancer stem cells." (PMID 37542193, 2023). "Expression of TACSTD2 was then compared to expression of CDH1 in breast cancer cell lines from The Cancer Cell Line Encyclopedia (CCLE) (N = 51) and The Library of Integrated Network-Based Cellular Signatures (LINCS) (N = 35)." (PMID 37567892, 2023). "Sublethal dosage of H2O2 distinctly decreased the expression of CDH1 (the coding gene of E-cadherin) at the mRNA and protein concentrations, promoting the migration of breast cancer cells." (PMID 37247842, 2023). "The levels of CDH1 mRNA were significantly upregulated in all subtypes of breast carcinoma, colon carcinoma, pancreatic carcinoma, and lung carcinoma and remained mostly unchanged in the subtypes of head/neck carcinoma and liver carcinoma." (PMID 37189027, 2023).
breast carcinoma (continued). "A recent publication highlighted a novel role of the E-cadherin (E-cad, encoded by CDH1 gene) expressing cells in breast cancer metastasis." (PMID 37006265, 2023). "Our study observed that the high level expressed SND1 in TNBC cell lines significantly increased the expression of DNMT3A, leading to aberrant methylation patterns of CDH1 and promoting breast cancer metastasis." (PMID 37885030, 2023). "MiR-152 targets DNMT1 and downregulates the expression of DNMT1, which helps restore cadherin 1 (CDH1) gene expression and obstructs the migration of breast cancer cells." (PMID 37298314, 2023). "Collectively, CDH1/2/4/11/12/13 are thought to be potential biomarkers for breast cancer progression and metastasis." (PMID 36315446, 2022). "We revealed that CDH1/2/4/11/12/13 messenger (m)RNA levels are overexpressed in breast cancer cells compared to normal cells and were correlated with poor prognoses in breast cancer patients’ distant metastasis-free survival." (PMID 36315446, 2022). "For example, inhibition of miR-9 (which in the case of breast cancer is characterized by overexpression) through the use of miRNA sponges (mimicking mRNA for cadherin-1) resulted in a reduction in metastasis." (PMID 35269947, 2022). "Over the years, with the increasing use of high-resolution quantitative methods for the detection of DNA methylation, the fraction of primary human breast cancer samples reported displaying CDH1 gene methylation continuously declined." (PMID 36139537, 2022). "Over the last 20 years, different, in part, even contradicting results have been published for the CDH1 gene in breast cancer." (PMID 36139537, 2022). "Of the 212,944 patients with cancer and available CDH1 sequencing data, 151,465 had breast cancer (71.1%), 27,915 had CRC (13.1%), 15,225 had ovarian cancer (7.1%), and 18,339 (8.6%) had other cancer types." (PMID 34949788, 2022). "In the frequently cited overview “A Gene Hypermethylation Profile of Human Cancer” by Esteller and colleagues in 2001, it is stated that the CDH1 gene is “hypermethylated” in 42% (37/88) of human breast cancer specimens." (PMID 36139537, 2022). "Particularly in human breast cancer, many different research groups have studied the inactivation of the CDH1 gene via DNA methylation using various methods." (PMID 36139537, 2022). "Polymorphism in the tumor suppressor gene TP 53, CDH1 and ATM genes are found to increase susceptibility for breast cancer globally." (PMID 36910346, 2022). "Again, these authors did not elaborate on the contradiction of CDH1 gene methylation and E-cadherin protein expression in the same breast carcinoma specimen." (PMID 36139537, 2022). "They found a CDH1 methylation rate of 67.57% (25/37) in Ca ex PA, similar to many other tumors such as primary lung cancer (88%), breast carcinoma (65–95%), and colorectal carcinoma (52%)." (PMID 35887973, 2022). "Although Cdh1 depletion had a negligible effect on the proliferation of breast cancer cell lines used in this study, it can significantly potentiate the cytotoxic effects of PARP inhibitors on TNBC cells." (PMID 35627188, 2022). "Ethanol-based garlic extract prevents breast cancer evolution driven by a hypoxia-induced decrease in CDH1 and increased vimentin and motility." (PMID 35464064, 2022).